MIR6794 (microRNA 6794)
Synonyms: hsa-mir-6794
Gene: MicroRNA gene on chromosome 19 (12,852,260 to 12,852,327, forward strand). Ensembl gene ENSG00000276181.
Homologues: Orthologues: chimpanzee MIR6794 (100% identical).